TRPM7 (transient receptor potential cation channel subfamily M member 7)
Description:
Bifunctional protein that combines an ion channel with an intrinsic kinase domain, enabling it to modulate cellular functions either by conducting ions through the pore or by phosphorylating downstream proteins via its kinase domain. The channel is highly permeable to divalent cations, specifically calcium (Ca2+), magnesium (Mg2+) and zinc (Zn2+) and mediates their influx. Controls a wide range of biological processes such as Ca2(+), Mg(2+) and Zn(2+) homeostasis, vesicular Zn(2+) release channel and intracellular Ca(2+) signaling, embryonic development, immune responses, cell motility, proliferation and differentiation (By similarity). The C-terminal alpha-kinase domain autophosphorylates cytoplasmic residues of TRPM7. In vivo, TRPM7 phosphorylates SMAD2, suggesting that TRPM7 kinase may play a role in activating SMAD signaling pathways. In vitro, TRPM7 kinase phosphorylates ANXA1 (annexin A1), myosin II isoforms and a variety of proteins with diverse cellular functions. [TRPM7 channel, cleaved form]: The cleaved channel exhibits substantially higher current and potentiates Fas receptor signaling. [TRPM7 kinase, cleaved form]: The C-terminal kinase domain can be cleaved from the channel segment in a cell-type-specific fashion. In immune cells, the TRPM7 kinase domain is clipped from the channel domain by caspases in response to Fas-receptor stimulation. The cleaved kinase fragments can translocate to the nucleus, and bind chromatin-remodeling complex proteins in a Zn(2+)-dependent manner to ultimately phosphorylate specific Ser/Thr residues of histones known to be functionally important for cell differentiation and embryonic development.
Synonyms: LTrpC-7; LTrpC7; CHAK1; TRP-PLIK; ALSPDC; CHAK
Tractability: Small molecule: a high-quality ligand is known; it belongs to a druggable protein family. Antibody: UniProt places it where antibodies can reach, with high confidence; its Gene Ontology location is reachable by antibodies, with high confidence; UniProt predicts a signal peptide or a membrane-spanning region; the Human Protein Atlas places it where antibodies can reach. PROTAC: it is named in the literature on targeted protein degradation; ubiquitination databases record sites on it; a small molecule that binds it is known.
Target class: Voltage-gated ion channel; Ion channel; Transient receptor potential channel
Gene: Protein-coding gene on chromosome 15 (50,552,473 to 50,686,797, reverse strand). Ensembl gene ENSG00000092439.
Subcellular location: Cell membrane; Cytoplasmic vesicle membrane; Nucleus (TRPM7 kinase, cleaved form)
Subcellular location (Human Protein Atlas): Plasma membrane; Vesicles; Cytosol; Nucleoplasm
Pathways (Reactome):
Transport of small molecules: TRP channels
Gene Ontology:
Molecular function: calcium channel activity; magnesium ion transmembrane transporter activity; protein binding; protein serine kinase activity; protein serine/threonine kinase activity; protein kinase activity; actin binding; ATP binding; calcium ion transmembrane transporter activity; kinase activity; myosin binding; zinc ion transmembrane transporter activity
Biological process: calcium ion transmembrane transport; magnesium ion homeostasis; magnesium ion transport; necroptotic process; calcium ion transport; intracellular magnesium ion homeostasis; monoatomic cation transmembrane transport; zinc ion transport; magnesium ion transmembrane transport; protein homotetramerization; protein tetramerization; zinc ion transmembrane transport
Cellular component: plasma membrane; cytoplasmic vesicle; cytoplasmic vesicle membrane; nucleus; membrane; ruffle
Genetic constraint (gnomAD): Loss-of-function variants: 104 observed, 179.8 expected, observed/expected ratio (o/e) 0.58, 90% interval 0.49 to 0.68. The upper end of that interval is the gene's LOEUF score, 0.68, which puts it in group 2 of 6, group 1 being the genes least tolerant of losing a copy. Missense variants: 1,642 observed, 1,959.4 expected, observed/expected ratio (o/e) 0.84, 90% interval 0.8 to 0.87. Synonymous variants: 598 observed, 638.98 expected, observed/expected ratio (o/e) 0.94, 90% interval 0.87 to 1.
Gene-disease validity (ClinGen):
ClinGen rates the evidence that TRPM7 causes each of these diseases.
macrothrombocytopenia, isolated (autosomal dominant): Moderate.
Homologues: Orthologues: chimpanzee TRPM7 (99% identical), macaque TRPM7 (99% identical), dog TRPM7 (97% identical), pig TRPM7 (95% identical), mouse Trpm7 (94% identical), rat Trpm7 (94% identical), rabbit TRPM7 (91% identical), guinea pig TRPM7 (88% identical), tropical clawed frog trpm7 (80% identical), zebrafish trpm7 (64% identical), tropical clawed frog XB5892783 (59% identical), Drosophila melanogaster Trpm (34% identical), and 4 more. Paralogues in human: TRPM6 (54% identical), TRPM3 (43% identical), TRPM1 (39% identical), TRPM2 (21% identical), TRPM4 (18% identical), TRPM5 (17% identical), TRPM8 (16% identical).
Diseases named in the same sentence as TRPM7 in open-access papers:
TRPM7 is named in the same sentence as 229 diseases in open-access papers, as found by Europe PMC text mining. Sharing a sentence is not in itself a finding about the gene and the disease. The quoted sentences say what the papers report.
breast carcinoma (76 papers, 2012 to 2025). "On the other hand, the activation of MAP kinase pathway via increased intracellular calcium levels in response to TRPM7 activation has also been proposed to cause an enhanced migration and invasion capacity of a human breast cancer cells in culture." (PMID 38255793, 2024). "TRPM7 activity was shown to be associated with metastatic potential and migratory properties in human breast cancer tissue and cells." (PMID 38255793, 2024). "Remarkably, in a Chinese population, an association between the single-nucleotide polymorphism of the TRPM7 gene and breast cancer has been observed." (PMID 38255793, 2024). "Further studies found that promoter methylation of TRPM7 were significantly associated with better clinical outcomes in breast cancer patients, especially in the Luminal A subtype." (PMID 36064388, 2022). "The Kaplan–Meier estimator of the survivorship function also indicated that TRPM7 methylation was negatively associated with longer survival time of breast cancer patients either after surgery or before disease recurrence." (PMID 36064388, 2022). "Another in vitro study showed that TRPM7 was associated with the growth of the human breast cancer cell line MCF-7." (PMID 34950031, 2021). "An in vitro study showed that TRPM7 is associated with the growth of the human breast cancer cell line MCF-7." (PMID 33435261, 2021). "The TRPM7 channel has been shown to be overexpressed in breast carcinoma with associated microcalcifications and it is an important player of Ca2+ and Mg2+ influx regulation in breast cancer." (PMID 34944940, 2021). "Two SNPs of TRPM7 have been shown to associate with breast cancer in Han population of northeast China, indicating the importance of TRPM7 in breast cancers progression." (PMID 32211326, 2020). "Inhibiting TRPM7 in breast cancer cell lines with 2-APB caused an increment in the percentage of cells in the S phase and a decreased cell population in the G0/G1 phase." (PMID 32643506, 2020). "A change in the level of expression occurred in pancreatic adenocarcinoma and breast cancer, and the mutation of TRPM7 was identified in colon cancer and ovarian carcinoma." (PMID 32168794, 2020). "Breast cancer patients with a high TRPM7 expression have a poor prognosis and TRPM7 single nucleotide polymorphisms (SNPs) are associated with breast cancer." (PMID 30615643, 2019). "Somatic mutations or polymorphisms of TRPM7 have been identified in breast carcinoma, gastric carcinoma, colon carcinoma, and ovarian carcinoma." (PMID 28379203, 2017). "Aberrant TRPM7 expression is associated with a number of cancers including breast carcinoma and head/neck cancer." (PMID 27835598, 2016). "In conclusion, the data indicated that TRPM7 genes polymorphism was likely associated with breast cancer in Han Population of Northeast China." (PMID 24952306, 2014). "The aim of this study was to evaluate the potential association of 8 TRPM7-tagging single-nucleotide polymorphisms (SNPs) with the risk of incident in breast cancer." (PMID 24952306, 2014). "Two of the TRPM7 SNPs (rs8042919 and rs7173321) are associated with breast cancer patients in Han Population of Northeast China." (PMID 24952306, 2014). "In this case–control study, we found that the rs8042919 (A/G) and rs7173321 (G/C) polymorphisms of TRPM7 gene were associated with breast cancer risk in Han Population of Northeast China." (PMID 24952306, 2014). "In breast cancer patients, high levels of TRPM7 mRNA expression were associated with higher incidence of recurrence and metastasis independently of standard clinical parameters." (PMID 23594099, 2013). "Indeed, variants in TRPM7 have been associated with increased susceptibility to a wide range of diseases, including neurodegenerative disorders, colorectal cancer, breast cancer and thrombocytopenia." (PMID 39099563, 2024).
breast carcinoma (continued). "A decrease in the expression of the TRPM7 protein, inducing a decrease in the metastatic potential of human breast cancer cells, indicates a causal effect between the expression levels of TRPM7 and the progression of breast cancer." (PMID 34944940, 2021). "The overexpression of TRPM7 may be associated with a poor prognosis in breast cancer patients, so more efforts are needed to research a new therapeutic target." (PMID 34944940, 2021). "A single nucleotide polymorphism of TRPM7 (T1482I) has been linked to an increased breast cancer risk and to the development of polyps that might progress to colon carcinoma." (PMID 34067290, 2021). "In addition, TRPM7 expression was positively associated with the size, stage, and histological grade in pancreatic adenocarcinoma and breast cancer in humans." (PMID 32168794, 2020). "Indeed, somatic mutation of TRPM7 has been found in breast carcinoma, colon carcinoma, ovarian cancer, and gastric carcinoma." (PMID 32907556, 2020). "TRPM7 has recently been linked to breast cancer cell proliferation." (PMID 30134548, 2018). "TRPM7 expression levels are increased in nasopharyngeal carcinomas and pancreatic ductal adenocarcinomas, and we showed in two independent cohorts that high TRPM7 expression associates with poor prognosis of breast cancer patients at time of diagnosis." (PMID 25797249, 2015). "It needs to be proved whether variant of T1482I can be induced by rs8042919 polymorphism in breast cancer patients, and variant of T1482I leads to changes in the structure and function of TRPM7 gene." (PMID 24952306, 2014). "However, it is surprising for us to find that there is weak association between TRPM7 genetic variants and breast cancer." (PMID 24952306, 2014). "Whether TRPM7 methylation predicts a better survival in patients with Lumina A breast cancers, as suggested by its association with clinicopathological characteristics of this subtype of breast cancer patients, was subsequently investigated by univariate and multivariable survival analysis." (PMID 36064388, 2022). "In addition, CNNM2 activity was suggested previously to regulate the TRPM7 magnesium channel that is associated with breast cancer growth and metastasis, which may also provide a third model of magnesium regulation in cancer by the PRL-CNNM complex." (PMID 26969161, 2016). "Thus, TRPM7 polymorphism might be one of candidates for the genetic marker to screen the risk of breast cancer." (PMID 24952306, 2014). "The findings suggest that TRPM7 plays a partial role in regulating EMT in breast cancer cells, while other calcium-permeable ion channels are also implicated in the induction of calcium-dependent EMT." (PMID 40078961, 2025). "The TRPM channels play a crucial role in modulating breast cancer metastasis, and the role of TRPM7 in particular in influencing metastasis in cancer has been explored in greater depth." (PMID 40078961, 2025). "For instance, TRPM7 was found to positively regulate cellular tension, modify FA number and change directed cell movement in breast cancer cells." (PMID 39436410, 2025). "In breast cancer cells, the TRPM7 kinase is involved in cell migration, metastasis formation and dissemination." (PMID 40274768, 2025). "The expression and/or the function of TRPM7 has been shown to be upregulated in many malignant cancer types, including colorectal carcinoma, prostate cancer, ovarian cancer, and breast cancer." (PMID 40813985, 2025). "Elevated mRNA expression of TRPM7 was found to significantly shorten the recurrence-free survival period among patients with primary breast cancer." (PMID 40078961, 2025). "Previously, the magnesium channel protein TRPM7 has been widely demonstrated to be involved in the development and progression of many cancers, including digestive system cancers, breast cancer and colorectal cancer." (PMID 41174507, 2025).
breast carcinoma (continued). "The ability of purified TRPM7 kinase domain to phosphorylate the CREB peptide led to the identification of TG100–115 as a new inhibitor of TRPM7 kinase activity and breast cancer cell migration." (PMID 41395111, 2025). "The de-adhesion and myosin II-based cell-substrate interactions in MDA-MB-213 breast cancer cells are found to be TRPM7-dependent." (PMID 40078961, 2025). "TRPM7 has already be shown to be involved in EMT of breast cancer cells by regulating calcium signaling and SOX4 transcription factor expression." (PMID 40274768, 2025). "Recently, there has been increased interest in TRP channels, which are overexpressed and dysregulated in various carcinomas, such as TRPC3 in ovarian cancer, TRPC6 in hepatocellular carcinoma, TRPM7 in breast cancer and TRPM8 in prostate cancer." (PMID 40813985, 2025). "Ki67 mitotic markers positively correlate with upregulated TRPM7 channels in breast cancer tissues, suggesting a role for this channel in breast cancer cell proliferation." (PMID 40078961, 2025). "A study utilizing a xenograft model of human breast cancer in mice demonstrated the key role of TRPM7 in tumor metastasis." (PMID 40078961, 2025). "TRPM7 silencing has been shown to inhibit breast cancer cell migration by increasing cell tension and focal adhesions." (PMID 40274768, 2025). "In another study, experiments with MCF-7 breast cancer cells demonstrated that TRPM7 regulates cellular levels of MDMX by modulating the intracellular Zn2+ levels." (PMID 39513908, 2024). "Recent studies showed that TRPM7 inhibitors interrupted the cell cycle, arresting the cells in the S phase, which suppresses the viability and migration of TRPM7 expressing breast cancer cells." (PMID 38255793, 2024). "The oncogenic roles and therapeutic potentials of TRPM7 in breast cancer are intensely investigated." (PMID 38255793, 2024). "The expression of the transcription factor Sex-determining region Y-related high-mobility group-BOX gene 4 (SOX4), a regulator of EMT in breast cancer cells, was promoted by TRPM7 via mechanical regulation by reducing myosin II-based cellular tension." (PMID 38255793, 2024). "TRPM7 regulates the migration and invasion of metastatic breast cancer cells through the MAPK pathway." (PMID 38706904, 2024). "A recent study has demonstrated that TRPM7 was highly expressed in the luminal A subtype of breast cancer." (PMID 38255793, 2024). "TRPC1 has been implicated in breast cancer cell proliferation, whereas TRPC6, TRPM7, and TRPV6 have demonstrated their involvement in the regulation of breast cancer cell proliferation and migration." (PMID 39334351, 2024). "Additionally, many investigators used NS8593 or other TRPM7 inhibitors, often in combination with RNAi silencing of TRPM7, to demonstrate the crucial role of TRPM7 in signaling pathways and cellular processes linked to tumor progression, including breast cancer." (PMID 39513908, 2024). "The functional expression of TRPM7 and thre regulation of tumor cell proliferation by this channel have been reported in human breast cancer cells." (PMID 38255793, 2024). "Collectively, our results reinforced the idea that TRPM7 represents a promising therapeutic target for treating breast cancer." (PMID 39513908, 2024). "Subsequently, a high expression of TRPM7 in human breast cancer cells and tissue, as well as its correlation with proliferation, has been repeatedly demonstrated." (PMID 38255793, 2024). "This mineralization is associated with poor prognosis and is suppressed by the inhibition of TRPM7 or the chelation of intracellular calcium in human breast cancer cells." (PMID 38255793, 2024). "The crucial role of HER2 in the diagnosis and treatment of breast cancer prompted us to study how TRPM7 regulates the expression of HER2." (PMID 39513908, 2024). "Both univariate and multivariate Cox regression showed that TRPM7 methylation was a potential predictor of better survival for the whole cohort breast cancer patients." (PMID 36064388, 2022).